NSG1 (neuronal vesicle trafficking associated 1)
Description:
Plays a role in the recycling mechanism in neurons of multiple receptors, including AMPAR, APP and L1CAM and acts at the level of early endosomes to promote sorting of receptors toward a recycling pathway. Regulates sorting and recycling of GRIA2 through interaction with GRIP1 and then contributes to the regulation of synaptic transmission and plasticity by affecting the recycling and targeting of AMPA receptors to the synapse (By similarity). Is required for faithful sorting of L1CAM to axons by facilitating trafficking from somatodendritic early endosome or the recycling endosome (By similarity). In an other hand, induces apoptosis via the activation of CASP3 in response to DNA damage.
Synonyms: D4S234; NEEP21; P21; D4S234E
Tractability: Antibody: UniProt places it where antibodies can reach, with medium confidence; UniProt predicts a signal peptide or a membrane-spanning region. PROTAC: ubiquitination databases record sites on it; its protein half-life has been measured.
Gene: Protein-coding gene on chromosome 4 (4,348,140 to 4,419,058, forward strand). Ensembl gene ENSG00000168824.
Subcellular location: Membrane; Golgi apparatus, trans-Golgi network membrane; Endosome membrane; Cell projection, dendrite; Early endosome membrane; Late endosome membrane; Lysosome lumen; Recycling endosome membrane; Cytoplasmic vesicle membrane; Golgi apparatus, Golgi stack membrane; Endosome, multivesicular body membrane; Endoplasmic reticulum membrane
Gene Ontology:
Molecular function: protein binding; clathrin light chain binding; ionotropic glutamate receptor binding; signaling receptor binding
Biological process: apoptotic process; amyloid precursor protein metabolic process; clathrin coat assembly; endosomal transport; neurotransmitter receptor cycle; postsynaptic neurotransmitter receptor cycle; receptor recycling; regulation of long-term synaptic potentiation; spontaneous synaptic transmission; neurotransmitter receptor transport, endosome to postsynaptic membrane; positive regulation of receptor recycling
Cellular component: endoplasmic reticulum; endoplasmic reticulum membrane; cytoplasm; cytoplasmic vesicle membrane; dendrite; early endosome membrane; endosome; endosome membrane; late endosome; late endosome membrane; lysosomal lumen; membrane; nucleus; recycling endosome membrane; somatodendritic compartment; trans-Golgi network membrane; early endosome; glutamatergic synapse; Golgi apparatus; Golgi cisterna membrane; lateral plasma membrane; multivesicular body membrane; postsynaptic endosome; postsynaptic membrane
Genetic constraint (gnomAD): Loss-of-function variants: 8 observed, 16.8 expected, observed/expected ratio (o/e) 0.48, 90% interval 0.28 to 0.86. The upper end of that interval is the gene's LOEUF score, 0.86, which puts it in group 3 of 6, group 1 being the genes least tolerant of losing a copy. Missense variants: 233 observed, 249.62 expected, observed/expected ratio (o/e) 0.93, 90% interval 0.84 to 1.04. Synonymous variants: 104 observed, 112.5 expected, observed/expected ratio (o/e) 0.92, 90% interval 0.79 to 1.09.
Homologues: Orthologues: chimpanzee NSG1 (100% identical), macaque NSG1 (100% identical), dog NSG1 (99% identical), rat Nsg1 (99% identical), mouse Nsg1 (98% identical), pig NSG1 (98% identical), guinea pig NSG1 (98% identical), tropical clawed frog nsg1 (66% identical). Paralogues in human: NSG2 (53% identical), CALY (38% identical).
Diseases named in the same sentence as NSG1 in open-access papers:
NSG1 is named in the same sentence as 21 diseases in open-access papers, as found by Europe PMC text mining. Sharing a sentence is not in itself a finding about the gene and the disease. The quoted sentences say what the papers report.
esophageal squamous cell carcinoma (4 papers, 2023 to 2025). Esophageal squamous cell carcinoma (ESCC) is a type of esophageal carcinoma (EC) that can affect any part of the esophagus, but is usually located in the upper or middle third. "In esophageal squamous cell carcinoma (ESCC), neuronal vesicle trafficking-associated protein 1 (NSG1) amplifies glycolysis and lactate production through activation of the TGF-β/p-SMAD2 axis, which drives epithelial–mesenchymal transition (EMT) and accelerates tumor progression." (PMID 41152975, 2025). "Increased Nsg1 expression is found in esophageal squamous cell cancer tissues, where it mediates invasiveness through activation of extracellular signal-regulated kinases (ERK) signaling." (PMID 38674069, 2024). "As a highly enriched endosomal protein within neuronal cells, NSG1 has been discovered to facilitate the process of epithelial-mesenchymal transition (EMT) in esophageal squamous cell carcinoma (ESCC)." (PMID 37872157, 2023).
Anxiety (3 papers, 2022 to 2024). Intense feelings of nervousness, tension, or panic often arise in response to interpersonal stresses. "NSG1 KO also caused increased anxiety in elevated mazes, and hyperactivity during subjective daytime, suggesting more global effects on cortical and subcortical networks." (PMID 35577358, 2022). "Together, these two complementary datasets support a role for NSG1 in circuits related to stress and anxiety, whereby loss causes increased anxiety specifically in elevated tasks." (PMID 35577358, 2022). "Thus, we undertook a series of behavioral tests on a newly generated NSG1 KO animal (see Section 2) to survey the impact of loss of NSG1 across motor, anxiety, and cognitive domains." (PMID 35577358, 2022). "NSG1 knockout (KO) also altered performance across other behavioral modalities including anxiety‐related and diurnal activity paradigms." (PMID 35577358, 2022). "Our previous work found that global knockout of NSG1 caused mild alterations in motor coordination, significant increases in anxiety-like behavior in elevated mazes, but no change in hippocampal- and amygdala-dependent learning and memory." (PMID 39257983, 2024). "Future studies using the conditioned eyeblink task across multiple NSG family member KO mice (e.g., NSG2‐3), could help determine whether the cerebellum may be a locus for anxiety‐related behavioral changes specifically in NSG1 KO mice." (PMID 35577358, 2022). "However, in more anxiety‐inducing tests such as the elevated plus and zero maze, NSG1 KO animals showed heightened anxiety‐like behaviors, and reduced time spent in the open regions." (PMID 35577358, 2022). "Interestingly, NSG3 OE animals do display similar phenotypes as NSG1 KO across motor and anxiety‐related domains." (PMID 35577358, 2022). "In contrast, NSG1 KO animals showed enhanced anxiety in similar tasks (EPM/EZM)." (PMID 35577358, 2022). "However, taken together, while NSG1 appears critical in motor and anxiety-related pathways, NSG2 and NSG3 may be primarily involved in associative learning and memory via differential AMPAR trafficking." (PMID 39257983, 2024). "We next used a complementary method to assess whether NSG1 KO truly displayed heighted anxiety." (PMID 35577358, 2022). "While knockout of NSG1 did impact motor coordination and anxiety, NSG1 KO animals showed no changes in learning and memory, despite its published role in synaptic plasticity." (PMID 39257983, 2024). "Surprisingly, we found that NSG1 KO animals displayed behavioral deficits across multiple motor and anxiety‐related domains, but were not impaired in hippocampal‐based learning and memory." (PMID 35577358, 2022). "This may be a critical component of the heightened anxiety phenotype observed on elevated tasks as the combination of the open (exposed) arms of the EPM and Zero Maze converge on circuitry that require NSG1 for normal function." (PMID 35577358, 2022). "Here we demonstrate that while KO of NSG1 does not significantly impact gross motor or cognitive function, NSG1 KO affects anxiety‐related behaviors, motor coordination, and circadian amplitude but not phase durations." (PMID 35577358, 2022). "However, together these data pointed to a possible increase in anxiety in NSG1 KO animals that was not statistically significant because of a potential floor effect given the limited time for all animals spent in the open arms." (PMID 35577358, 2022).
colon cancer (2 papers, 2020 to 2024). "One study found that NSG1-IgG was elevated in the serum of patients with early-stage colon cancer and was a predictive marker." (PMID 38892156, 2024).
lung carcinoma (2 papers, 2022 to 2025).
esophageal cancer (1 paper, 2024). A primary or metastatic malignant neoplasm involving the esophagus. "For example, NSG1 expression is significantly increased in the tissues of patients with esophageal cancer and colorectal cancer." (PMID 38892156, 2024). "Another study found that NSG1 can promote the malignant behavior of esophageal cancer cells and can activate the ERK signaling pathway, which also provides information for our subsequent exploration of signaling pathways." (PMID 38892156, 2024).
frontotemporal dementia (1 paper, 2023). Frontotemporal dementia (FTD) comprises a group of neurodegenerative disorders, characterized by progressive changes in behavior, executive dysfunction and language impairment, as a result of degeneration of the medial prefrontal and frontoinsular cortices. "However, using cell surface biotinylation, we found only NSG1 reduced sortilin cell surface expression, which caused significant reductions in uptake of progranulin, a molecular determinant for frontotemporal dementia." (PMID 37949230, 2023).
head and neck squamous cell carcinoma (1 paper, 2024). A squamous cell carcinoma that arises from any of the following anatomic sites: lip and oral cavity, nasal cavity, paranasal sinuses, pharynx, larynx, and salivary glands. "To further validate the role of NSG1 in the invasion of head and neck squamous cell carcinoma cell lines, we overexpressed NSG1 in the HSCC cell lines FaDu and D562 and observed its phenotype." (PMID 38892156, 2024).
leukemia (1 paper, 2025). A malignant (clonal) hematologic disorder, involving hematopoietic stem cells and characterized by the presence of primitive or atypical myeloid or lymphoid cells in the bone marrow and the blood. "Four of these genes were reported for leukemias (IRS1, RUNX2, CCDC50 and ROBO3) and four others were reported to be involved in other types of cancers (NSG1, CAMK1D, CD3E, KLF8)." (PMID 41146244, 2025).
ovarian carcinoma (1 paper, 2026). A malignant neoplasm originating from the surface ovarian epithelium. "Among the genes we identified in this study, IL7R, IRF8, PTPRC, and NSG1 have not been thoroughly explored or recognized for their relevance in ovarian cancer recurrence in previous studies." (PMID 41596598, 2026).
periodontitis (1 paper, 2022). An acute or chronic inflammatory process that affects the tissues that surround and support the teeth. "BTG2 and NSG1 play an important role in apoptosis, and apoptosis is clearly involved in periodontitis and can serve as a biomarker." (PMID 36457739, 2022). "Among the 13 periodontitis biomarkers, BTG2 and NSG1 were identified for the first time." (PMID 36457739, 2022). "The results suggested that NEFL and NSG1 may be negative immune regulators in periodontitis, while other biomarkers may be active immune regulators." (PMID 36457739, 2022).
pharyngeal cancer (1 paper, 2024). "To discover the downstream mechanism of NSG1 that regulates the growth of pharyngeal cancer cells, we observed the expression of ERK pathway proteins in the treated cells." (PMID 38892156, 2024).
steatosis (1 paper, 2021). Increased lipid within the cytoplasm of cells. "On the other hand, both steatosis and inflammation infiltration in the liver of NASH rats were significantly alleviated by the treatment of SV (NS), GJ (NG1), and their combination (NSG1)." (PMID 33967756, 2021).
type 2 diabetes (1 paper, 2018). "Nine genes not previously reported to be associated with type 2 diabetes were significantly dysregulated in our organ donor and PPP cohorts (ANKRD23/39, ASCL2, HHATL, NSG1, PCDH20, SCTR, CD44, FAM102B and FBXO32)." (PMID 29185012, 2018).
tumor (5 papers, 2023 to 2026). "Consistent with that mechanism, low NSG1 expression—as observed in our study—is associated with impaired tumor suppressor function and poor prognosis." (PMID 41596598, 2026). "By analysis of the clinical characteristics of ESCC, high NSG1 level was positively associated with tumor T staging." (PMID 37872157, 2023). "Additionally, high NSG1 expression was shown to be associated with tumor size, indicating that NSG1 might be responsible for the proliferation of ESCC cells." (PMID 37872157, 2023). "Through that regulation, NSG1 modulates intracellular signaling pathways that influence tumor cell proliferation, migration, and progression." (PMID 41596598, 2026). "NSG1 overexpression reduces tumor cell viability, potentially by inducing endoplasmic reticulum stress." (PMID 41596598, 2026). "The relative expression levels of NSG1 in HSCC tissue (n = 6) and adjacent non-malignant hypopharyngeal tissue (n = 6) were then determined using immunohistochemical methods, confirming the high levels of the NSG1 expression in the tumor tissue." (PMID 38892156, 2024). "Further analysis revealed an abnormal upregulation of NSG1 expression in cancerous tissues compared to the surrounding non-tumor tissues." (PMID 37872157, 2023). "These outcomes not only validate the role of the NSG1/TGF-β axis in enhancing tumor glycolysis and promoting ESCC progression, but also offer additional insight into ESCC development." (PMID 37872157, 2023). "Conversely, the primary tumor-specific DEG NSG1 did not exhibit significant associations with protein expression in primary tumors." (PMID 41596598, 2026). "Beyond its tumor-intrinsic role, NSG1 also influences the TME." (PMID 41596598, 2026). "Functional validation further demonstrated that IL7R, IRF8, and PTPRC contribute to tumor progression by promoting immune evasion, whereas NSG1 might have tumor-suppressive effects." (PMID 41596598, 2026). "Finally, to investigate the impact of the NSG1/TGF-β axis on tumor development in vivo, a xenograft model featuring stable NSG1 overexpression was established." (PMID 37872157, 2023). "Considering that TGF-β is vital for the regulation of LDHA and tumor migration, we deduced that the NSG1/TGF-β axis might induce an EMT-like phenotype in ESCC cells by activating LDHA." (PMID 37872157, 2023). "The results showed that NSG1 overexpression boosted tumor weight, volume, and Ki-67 expression, while SB-431542 treatment inhibited the ability of NSG1 on tumorigenesis in vivo, demonstrated that NSG1/TGF-β axis is indispensable signaling for proliferation of ESCC cells." (PMID 37872157, 2023). "In contrast, reduced NSG1 expression leads to decreased CHOP activation and weakened apoptotic responses to DNA damage, promoting tumor survival." (PMID 41596598, 2026). "Low NSG1 expression correlates with reduced infiltration of CD8+ T cells and M1 macrophages and increased activation of M2 macrophages, thereby contributing to immune evasion and tumor progression." (PMID 41596598, 2026). "Recent study revealed that NSG1 might participate in the tumor occurrence and development by influencing the JAK/STAT signaling pathway and cyclin D1, whereas the role of NSG1 on ESCC development remains to be uncovered." (PMID 37872157, 2023).
cancer (4 papers, 2020 to 2025). A tumor composed of atypical neoplastic, often pleomorphic cells that invade other tissues. "The CCK-8 experiment showed that silencing NSG1 significantly weakened the survival ability of the cancer cells and reduced the cell viability." (PMID 38892156, 2024). "The CCK-8 experiment showed that the overexpression of NSG1 enhanced the proliferation ability of cancer cells and reduced the cell viability." (PMID 38892156, 2024). "However, in recent years, increasingly more studies have been conducted on the relationship between NSG1 and the occurrence and development of malignant tumors." (PMID 38892156, 2024). "Since the enhancement of cell viability, migration, and invasion is closely related to the malignant phenotype of cancer cells, the expression of NSG1 may potentially promote the occurrence and development of HSCC." (PMID 38892156, 2024). "Here we discovered that high NSG1 expression existed in both cancer tissues and cancer cell lines." (PMID 37872157, 2023). "Subsequently, we assessed the NSG1 expression in the obtained cancer and adjacent non-malignant hypopharyngeal tissue through qPCR, Western blot, and immunohistochemistry." (PMID 38892156, 2024). "Because the ERK pathway is a classical pathway for the development of malignant tumors, we also detected the expression of ERK pathway proteins in cell lines that knocked down and overexpressed NSG1, and found that the change trend of P-ERK expression was consistent with that of NSG1." (PMID 38892156, 2024).
neurological diseases (2 papers, 2022). "As sleep–wake cycles and circadian rhythms have become increasingly associated with neurological disorders, we used homecage monitoring to determine whether loss of NSG1 causes alterations in sleep–wake activity across several circadian cycles." (PMID 35577358, 2022).
NSG1 also shares sentences with these, for which no sentence is quoted: Bacterial Infections (1 paper); channelopathies (1); hypopharyngeal cancer (1); Hypopharyngeal Squamous Cell Carcinoma (1); neuropathy (1).